INS (insulin)
Diseases named in the same sentence as INS in open-access papers (continued):
Sharing a sentence is not in itself a finding about the gene and the disease.
diabetes (continued). "A far more accurate marker for insulin resistance is the HOMA-IR score, which in adolescents with weight excess is known to be a trustworthy proxy for estimating the resistance to insulin activity, powerfully predicting the risk of developing diabetes mellitus type 2." (PMID 36832311, 2023). "Overall, both “double diabetes” and fasting are associated with changes in insulin resistance and glucose metabolism at the cellular level and thus may theoretically establish a relationship between fasting and double diabetes at the cellular level." (PMID 37630716, 2023). "Insulin resistance (IR), a state of impaired biological response to normal circulating levels of insulin, represents an early pathophysiology of diabetes progression and is associated with micro and macrovascular diseases, as reported by cross-sectional epidemiologic studies." (PMID 37974292, 2023). "The reduced expression of PARs following both Mg2+ and insulin treatments in the present study may be associated with improved diabetes-induced gastric damage." (PMID 37228689, 2023). "HO-1 also has an effect on insulin sensitivity; induction of HO-1 expression increased insulin sensitivity, reduced adipose tissue volume, caused adipose tissue remodeling, and improved hyperinsulinism of insulin resistance in diabetes." (PMID 37675385, 2023). "Metabolic disorders such as diabetes mellitus (DM), which is associated with impaired insulin secretion (type 1 diabetes) or peripheral insulin resistance (type 2 diabetes), can disrupt this control, resulting in a prolonged increase in plasma glucose level or hyperglycemia." (PMID 37507997, 2023). "In the context of diabetes, inflammation is one of the key underlying factors, with low-grade systemic inflammation being an early and primary pathological event that contributes to the development of IR in various insulin-sensitive tissues." (PMID 38068866, 2023). "Impaired insulin secretion is a hallmark in type 2 diabetes mellitus (T2DM)." (PMID 36823211, 2023). "Selenoprotein P (SelP), a selenium-supply protein, is hypothesized to raise the risk of diabetes by promoting insulin resistance and dysregulating glucose metabolism." (PMID 37275636, 2023). "Diabetes, which affects nearly 10.5% of the population worldwide, is a chronic metabolic disease characterized by hyperglycemia caused by insulin resistance, a deficiency in insulin secretion, or both." (PMID 36615556, 2023). "Insulin use also significantly increases the risk of diabetes among patients." (PMID 37237354, 2023). "In most cases, there are precipitating factors, which could be: underlying infection, missed insulin treatment, previously unknown diabetes, surgical stress, etcetera." (PMID 37363479, 2023). "Biological mechanisms which support this include worsening insulin resistance, likely associated with abnormalities in insulin signalling pathways affecting systemic metabolism and cerebral insulin signalling, and possibly microvascular disease, a known risk factor of diabetes and dementia." (PMID 36869989, 2023). "Also, glucocorticoids inhibit the synthesis and secretion of pancreatic insulin, induce pancreatic β cell apoptosis, loss of β cell function and the subsequent development of diabetes." (PMID 37628857, 2023). "In pancreatic β-cells, mGPDH and glycerophosphate shuttle mediate the glucose-dependent insulin secretion process, and the accumulation of damaged or depolarized mitochondria in β-cells is associated with oxidative stress and the development of diabetes mellitus." (PMID 36979626, 2023). "As rare variants associated with neonatal diabetes were identified to induce additional de novo splice alterations, there is a further need for surveillance within neonatal diabetes for splice-altering INS variants." (PMID 36830626, 2023). "Diabetes has a complicated polygenic nature, with most loci increasing diabetic risk by directly affecting insulin secretion and a minority acting by decreasing insulin action." (PMID 38001980, 2023).
diabetes (continued). "Type 2 diabetes patients with high polygenic risk (N = 1008) had earlier onset of diabetes (58.5 years vs. 61.0 years, p = 5.2e-04) and were more likely to be on insulin therapy (42.6% vs. 30.5%, p = 1.2e-04) compared to type 2 diabetes patients with low polygenic risk (N = 321)." (PMID 37852978, 2023). "Excessive release of insulin depletes β-cells, which is the main cause of diabetes." (PMID 37835312, 2023). "Furthermore, oxidative stress can be implicated in insulin resistance, inflammation in neural tissues, and lipid metabolism disorders, affecting cognitive dysfunction in diabetics." (PMID 37077347, 2023). "One potential mechanism explaining the association between birthweight, diabetes, and the gene is the fetal insulin hypothesis." (PMID 36609580, 2023). "Abnormal insulin level in the blood is the main cause of diabetes." (PMID 36978970, 2023). "Diabetes mellitus is a metabolic disease associated with the abnormal or faulty digestion of carbohydrates, fat, and protein metabolism, leading to either disrupted glucose homeostasis or impaired insulin secretion." (PMID 38020229, 2023). "Insulin is widely used and sometimes the only option for patients with diabetes and liver dysfunction, while there is a concern that insulin might increase the risk of cancer through its mitogenic effects." (PMID 37852976, 2023). "The activation of the hY1 receptor harms insulin secretion from beta-cells, and it was observed in mice that by transplanting islets with a deficiency of Y1 receptors, normoglycemia can be faster restored in alloxan-induced diabetes." (PMID 36834796, 2023). "Smart connected insulin pens and use of digital technology are associated with improved glycemic control; but may also improve the quality of life of people with diabetes by reducing their treatment burden." (PMID 36828942, 2023). "Breastfeeding may have a positive effect on glucose metabolism and insulin sensitivity, which may reduce the risk of developing diabetes following gestational diabetes mellitus (GDM)." (PMID 38004222, 2023). "This correlation could influence insulin secretion and potentially lead to type 2 diabetes mellitus, a known risk factor for PDR." (PMID 38274229, 2023). "Additionally, we assessed the risk of insulin requirement and diabetes-associated complications in cancer survivors, compared with participants without cancer during a 10-year follow-up period." (PMID 36831436, 2023). "In type 2 diabetes mellitus (T2DM), which is linked to genetics and lifestyle habits, cells do not respond adequately to insulin (insulin resistance), whereas type 1 diabetes mellitus (T1DM) is caused by an autoimmune response which attacks insulin-producing cells (β-cells)." (PMID 37958667, 2023). "Regular PA is considered essential in the management of diabetes as it can prevent or delay the onset of diabetes, reduce other cardiovascular risk factors, contribute to weight loss, improve insulin sensitivity, reduce HbA1c levels, and increase the quality of life of these patients." (PMID 36983443, 2023). "Diabetes Mellitus (DM) is caused by irregular blood glucose levels due to insulin deficiencies." (PMID 37570359, 2023). "Controversially, in a cross-sectional study, insulin treatment was one of the risk factors for age-related muscle atrophy in those with diabetes, while in a longitudinal study, insulin treatment and correction of glycemic level attenuated the progression of sarcopenia." (PMID 36769296, 2023). "Our two-sample MR study aimed to reveal causal relationships between two diabetes types: type 1 and 2 diabetes, and four glycemic traits: fasting insulin (FIns), fasting glucose (FGlu), 2 h-glucose post-challenge (2hGlu) and glycated hemoglobin (HbA1c) with these CMR features." (PMID 38066511, 2023). "Diabetes mellitus may cause hypomagnesemia, via poor dietary intake, increased renal losses, impaired insulin secretion and insulin resistance." (PMID 36794273, 2023).
diabetes (continued). "Studies conducted thus far have implicated inhibition of insulin-dependent glucose uptake, pancreatic β-cell damage and/or dysfunction, and stimulation of hepatic gluconeogenesis as some of the major mechanisms involved in iAs-induced diabetes." (PMID 37886432, 2023). "Diabetes mellitus (DM) is a severe and chronic metabolic disease characterized by increased blood glucose levels due to an imbalance in glucose homeostasis caused by reduced insulin secretion, insulin resistance (IR), or a combination of these factors." (PMID 37754257, 2023). "Counterregulation of plasma glucose by insulin and glucagon is a well-characterized phenomenon in normal physiology, while dysregulation of these hormones leads to dysglycemia and is a hallmark of diabetes." (PMID 37660302, 2023). "Indeed, streptozocin enters the pancreatic β-cell via the GLUT2 transporter and causes DNA alkylation leading to insulin resistance and the progressive destruction of pancreatic cells with the consequent onset of diabetes." (PMID 37674975, 2023). "Individuals with diabetes, specifically those with type 1 diabetes who administer multiple daily insulin injections or utilize an insulin pump, are susceptible to experiencing severe hypoglycemia or abnormally low blood sugar levels (commonly referred to as insulin shock)." (PMID 38132485, 2023). "The cognitive burden associated with self-management of diabetes therapy may influence preferences for advanced insulin delivery systems." (PMID 36828942, 2023). "At the same time, GPR119 activation also increases glucagon secretion, which may reduce the risk of medically induced hypoglycemia in patients with diabetes undergoing intensive insulin therapy." (PMID 37686185, 2023). "In particular, insulin users in the diabetes < 5 years group had a significantly higher AP risk." (PMID 37208706, 2023). "Therefore, both can be indirectly associated with diabetes mellitus because diabetes mellitus, especially type 2, is caused by insulin resistance and the body cannot produce insulin." (PMID 37372155, 2023). "It was hypothesised that such antibodies may underlie ‘brittle diabetes’, although the potential of antibodies to enhance glucose control by sustaining insulin action was also noted." (PMID 37562398, 2023). "Consequently, a high-fiber diet has been shown to lower serum triglycerides and systolic blood pressure, adiposity and inflammation, all of which lead to improved insulin sensitivity and a reduced risk of developing diabetes and its complications." (PMID 37960272, 2023). "Long-term hypersecretion of insulin could deplete β-cell reserves and consequent insulin-deficient states, which in turn lead to major metabolic disturbances such as diabetes." (PMID 36992977, 2023). "Diabetes is associated with a series of complex and chronic disorders characterized by indicative glucose intolerance and ensuing from absolute or relative imbalanced insulin secretion or insulin action." (PMID 37049866, 2023). "Some studies show that fluctuation of trace elements and elevated oxidative stress may cause insulin dysfunction, diabetes, and diabetes complications." (PMID 35303254, 2023). "Type 2 diabetes mellitus (T2DM) is classified as a complicated heterogeneous group of metabolic disorders that are characterized by unusually high blood glucose levels (hyperglycemia) from deficiencies in insulin action, insulin secretion, or both." (PMID 36500221, 2022). "However, this situation is desired in diabetes treatment since the control action is precisely canceled when a risk of hypoglycemia is predicted, and therefore, insulin administration must be reduced or suspended." (PMID 35265035, 2022). "Also, a study on the Asian population considers insulin-independent diabetes as an independent risk factor for the development of DVT and PE." (PMID 35887630, 2022).
diabetes (continued). "Reduced insulin sensitivity might occur in the earliest phase of m.3243A>G-associated diabetes, while the occurrence of decreased insulin secretion depends on the heteroplasmy level and the progression of diabetes." (PMID 36276941, 2022). "A recent work showed that fatty acids released from pancreatic adipocytes may cause insulin hypersecretion in islets isolated from a diabetes prone mouse model." (PMID 36138030, 2022). "Diabetes is a metabolic disease characterized by elevated blood glucose concentrations as a consequence of an absolute deficiency of insulin secretion or inadequate insulin secretion to compensate for ineffective insulin action." (PMID 35200143, 2022). "On the other hand, subcutaneous applications of insulin during the treatment of diabetes may cause insulin-derived amyloidosis characterized by the formation of insulin amyloid fibrils at the site of repeated injections." (PMID 36060240, 2022). "Diabetes mellitus is one of the most common endocrine metabolic disorders characterized by chronic hyperglycemia caused by varying degrees of insulin resistance, deficiency in insulin secretion, or both." (PMID 35807526, 2022). "Diabetes confers a 1.3 to 1.9-fold increased risk of cognitive impairment, but even pre-diabetes and diabetes-associated biochemical changes (fasting glucose, postload glucose, glycosylated hemoglobin, insulin) predict cognitive decline." (PMID 35860697, 2022). "In fact, KS could have effects on body composition, insulin sensitivity, bone metabolism and cardiovascular morbidity, with an increased risk of diabetes, metabolic syndrome, osteoporosis and cardiac disease." (PMID 35631248, 2022). "Additionally, HD is not only associated with altered insulin metabolism and diabetes mellitus, but also has a neuroinflammatory component that plays a relevant role in the development and progression of the disease." (PMID 35615716, 2022). "Impaired insulin signaling increases risk of AD and cognitive disabilities in diabetes mellitus." (PMID 35264925, 2022). "The most significant clinical indicator of diabetes is persistent hyperglycemia which is caused by either the failure of the pancreas to secrete sufficient insulin or by decreased sensitivity of target organs to insulin which is known as insulin resistance." (PMID 36432581, 2022). "From a pathophysiological perspective, since the primary actions of metformin significantly reduce circulating glucose and plasma insulin, hence improving insulin resistance, it may be beneficial for reducing the risk of diabetes-related cancer incidents." (PMID 35956087, 2022). "Type 2 diabetes mellitus (T2D) was a metabolic disease caused by impaired insulin action." (PMID 36131931, 2022). "Underlying biological differences in glucose or insulin metabolism and genetic factors may differentially impact risk for diabetes as well as other factors, including socioeconomic factors and differences in cultural eating patterns." (PMID 36131333, 2022). "IR is defined as an impaired response towards insulin stimulation by the target tissues and could cause many diseases including diabetes." (PMID 35744089, 2022). "Low-quality and dysfunction of pancreas and Langerhans islets could cause insufficient secretion of insulin, promoting the development of diabetes mellitus." (PMID 36140883, 2022). "The significant medication of the association between FPG variability and diabetes risk by changes in HOMA‐IR, as found in the current study, provided further evidence that glucose variability leads to increased diabetes risk through worsening of insulin sensitivity." (PMID 35170854, 2022). "However, insulin therapy in diabetes causes body weight and fat mass gain owing to its anabolic effect and dietary compensation for hypoglycemia." (PMID 36463197, 2022).
diabetes (continued). "One of several plausible links between diabetes and colorectal cancer could be related to insulin resistance and hyperinsulinemia, a state of heightened insulin levels and a hallmark of untreated type 2 diabetes in its earlier natural history." (PMID 35383926, 2022). "The study aimed to test the hypothesis that homeostatic microbiome (HM) disorders lead to the increased indirect influence of certain microorganisms (MO) in the gastrointestinal tract, causing a disorder of insulin secretion, insulin resistance, and diabetes." (PMID 36397429, 2022). "Indeed, fumarase deletion in mouse pancreatic beta cells led to elevated fumarate levels and enhanced protein succination, which were associated with decreased insulin secretion and the development of diabetes." (PMID 35327418, 2022). "Similarly, in another cross-sectional study carried out in Saudi Arabia in 2014, which included 552 patients with diabetes, insulin use was found to be associated with DN." (PMID 36348847, 2022). "Diabetes mellitus is caused by an insufficient action or decreased production or of insulin." (PMID 35730406, 2022). "Several lines of studies have shown that central infusion of leptin is able to normalize hyperglycemia in rodents with severe insulin-deficient diabetes for couples of days, and this ameliorative effect is achieved through an insulin-independent increase of glucose disposal." (PMID 35619170, 2022). "One of the causes of diabetes in infants is the defect of the insulin gene (INS)." (PMID 35955956, 2022). "By comparing the clinical features of children with an INS mutation with those with early-onset diabetes due to KATP channel mutations in our cohort we found that those with INS mutations presented with diabetes later (mean age 20 + 17 weeks vs 8.7 + 5.1, p=0.012)." (PMID 35518939, 2022). "By neutralizing free radicals, reducing lipid peroxidation and promoting insulin secretion, FA reduces the β-cell dysfunction caused by diabetes and the excessive production of free radicals, which is also related with its inhibition of the excess production of TG or FFA caused by diabetes." (PMID 36144745, 2022). "Diabetes mellitus is caused by dysfunction or death of insulin-producing β cells in the pancreas." (PMID 37193354, 2022). "Diabetes may be associated with impaired liver production of albumin because insulin is an important regulator of its synthesis." (PMID 35831938, 2022). "Obesity and diabetes are both associated with metabolic changes such as increasing circulating levels of leptin and insulin, which may adversely impact development." (PMID 36337853, 2022). "Furthermore, the beneficial effects of the increase in hepatic glycogen have also been demonstrated in an animal model of insulin-deficient and monogenic diabetes, namely the Akita mouse." (PMID 36157460, 2022). "The mechanism by which the FIB‐4 index enhances the risk of diabetes mellitus onset in individuals with FLD might be associated with its effect on insulin secretion." (PMID 35437902, 2022). "Identification of insulin as upstream regulator in SCC points out well described relationship between diabetes mellitus and cancers, including lung cancer, and hyperinsulinemia and exogenous insulin and insulin analog therapy were indicated as common risk factors for development of cancer." (PMID 35512017, 2022). "Obesity is recognized as the most powerful environmental risk factor among several modifiable risk factors for diabetes, which is associated with an increased insulin demand and increased likelihood of insulin resistance leading to prediabetes or hyperinsulinemia and ultimately T2DM." (PMID 35495951, 2022). "The presence of familial diabetes is essential to be investigated, in order to choose the most suitable supplementary treatments, since predisposition to diabetes leads to an impaired expression/function of specific components of insulin signaling or enzyme, such as epimerase and LASY." (PMID 36009471, 2022).